ENSG00000201133
Synonyms: LOC124900241
Gene: Small nucleolar RNA gene on chromosome 7 (50,935,350 to 50,935,493, reverse strand). Ensembl gene ENSG00000201133.
Gene Ontology:
Biological process: RNA processing
Cellular component: nucleolus
Homologues: Orthologues: rat LOC120099067 (66% identical), rat LOC120100360 (63% identical), mouse Gm24728 (57% identical), rat LOC120095411 (56% identical), mouse Gm54692 (56% identical), rat LOC120099453 (53% identical), rat LOC120102009 (44% identical). Paralogues in human: SNORA4 (77% identical).